STAT3 (signal transducer and activator of transcription 3)
Diseases named in the same sentence as STAT3 in open-access papers (continued):
Sharing a sentence is not in itself a finding about the gene and the disease.
tumor (continued). "Clinical observations further indicate that it suppresses key tumor-promoting pathways such as mTOR and STAT3." (PMID 41010968, 2025). "Exosomal lncRNA-ARSR derived from renal cell carcinoma directly interacts with miR-34/miR-449, increases STAT3 expression, promotes M2 polarization of macrophages, and exhibits a phenotype that promotes angiogenesis and tumor growth." (PMID 40612677, 2025). "Second, GDF15 binds to its receptor GFRAL and activates a chronic inflammatory response via the PI3K/AKT/STAT3 pathway, which induces an imbalance in oxidative stress, resulting in increased tumor burden and drug resistance." (PMID 41035818, 2025). "Prohep also downregulated c-jun and c-fos expression levels which functioned as the effectors of STAT3-induced tumor cell proliferation." (PMID 39641861, 2025). "While multiple kinases contribute to the activation of STAT3, JAK2 stands out as a critical upstream molecule that governs STAT3 activation within a variety of tumor cells." (PMID 40051568, 2025). "Highly absorptive forms of curcumin were shown to augment anti-PD-1 therapy by inhibiting STAT3 activation in dendritic cells and tumor cells, thereby restoring T-cell stimulatory activity and enhancing antitumor responses." (PMID 40575656, 2025). "As an oncogene, STAT3 is overexpressed in tumor biopsies from patients with CRC 14 and is activated during colorectal tumorigenesis." (PMID 41281755, 2025). "VEGF is known to upregulate PRD1-BF1/Blimp1 expression in tumor vasculature through signaling pathways mediated by Erk1/2 and Stat3, thereby increasing the sensitivity of tumor vasculature to Vaccinia virus (OVVs) infection." (PMID 40612869, 2025). "Research has shown that elevated STAT3 activity contributes significantly to tumor growth and development." (PMID 41551164, 2025). "TAM-derived LGMN increases macrophage infiltration and tumor progression through the GSK3β/STAT3 axis." (PMID 40131864, 2025). "Research has shown that STAT3, a key member of this family, is frequently overexpressed and constitutively active in various tumor cells and tissues." (PMID 40906092, 2025). "Quercetin treatment also leads to a decrease in the release of IL-6 and the phosphorylation of STAT3, suggesting interference with signaling pathways that promote tumor growth and survival." (PMID 41009025, 2025). "Twist is another EMT transcriptional factor, and the interaction between STAT3 and Twist can affect tumor metastasis." (PMID 40830747, 2025). "Modified with EGFR-targeting aptamers, these STAT3/EKEVs showed high stability, specificity, and effectiveness, significantly suppressing tumor growth in a mouse model through STAT3 inhibition." (PMID 39744221, 2025). "Recent preclinical studies have expanded the therapeutic landscape by demonstrating that targeting TNF-α or its downstream pathways such as STAT3 and CSF-1 can significantly reduce tumor growth and metastatic potential." (PMID 40558596, 2025). "These cytokines activate signaling pathways such as SMAD, STAT3, and NF-κB in tumor cells, leading to the downregulation of epithelial markers like E-cadherin and the upregulation of mesenchymal markers such as vimentin and N-cadherin." (PMID 39983469, 2025). "Results of the IHC analysis revealed upregulation of STAT3 phosphorylation in tumor tissues in which HRH1 was knocked down." (PMID 40113769, 2025). "For example, IL-27 predominantly mediates the regulation of inflammation within the tumor microenvironment through the downstream JAK/STAT3 pathway, thereby influencing tumor cell invasiveness." (PMID 40699663, 2025). "STAT3 modulates numerous pathways critical for tumor survival, including apoptosis inhibition, immune evasion, angiogenesis, and EMT." (PMID 40075607, 2025). "Upon ligand-receptor binding, tumor-derived IL-6 plays a crucial role in promoting MDSC chemotaxis within the TIME by activating the JAK/STAT3 and NF-κB signaling pathways." (PMID 41326342, 2025).
tumor (continued). "Studies have shown that curcumin can reduce the number of M2 macrophages and increase the proportion of M1 macrophages by inhibiting the STAT3 signaling pathway, thereby restoring anti-tumor immune responses." (PMID 40989587, 2025). "The phosphorylated STAT3 has been reported to be acetylated by acetyltransferase to regulate tumor progression." (PMID 39643827, 2025). "Emerging evidence suggests that STAT3 plays a crucial role in modulating immune responses related to tumor development and immune suppression." (PMID 40166646, 2025). "The activation of STAT3 promotes the expression of a variety of genes, including VEGF, MMPs, and cyclin D1, which are associated with tumor angiogenesis, invasion, and progression." (PMID 40850976, 2025). "This process activates STAT3 phosphorylation and induces macrophage polarization toward the pro-tumor M2 phenotype." (PMID 40612677, 2025). "This is particularly evident in malignancies such as hepatocellular carcinoma, glioblastoma, and breast cancer, where STAT3 contributes to the self-renewal, survival, and chemoresistance of tumor-initiating cell populations under oxidative conditions." (PMID 40867898, 2025). "STAT3 is also involved in regulating lipid metabolism in tumour cells, affecting lipid synthesis, breakdown and uptake." (PMID 39778006, 2025). "Research on PDA has shown that honokiol interferes with oncogenic signaling networks—namely STAT3 and NF-κB—thereby inhibiting tumor cell proliferation and enhancing apoptosis." (PMID 40427617, 2025). "LCN2 binds to SLC22A17 receptors on fibroblasts, activating STAT3, which further enhances fibroblast proliferation and secretion of MMPs and IL-6, reinforcing tumor growth and inflammation." (PMID 40472740, 2025). "Mechanistically, leucine-rich repeat–containing GPCR5 (Lgr5+ ) cancer stem cells induced OX40 expression in tumor ECs via EGF/STAT3 signaling." (PMID 40026246, 2025). "In contrast, STAT3 supports oncogenesis by inhibiting apoptosis, enhancing cell proliferation, and modulating anti-tumor immune responses through inflammatory suppression and regulatory T-cell expansion." (PMID 40775363, 2025). "Our findings confirm the well-established relationship between STAT3 and tumor cell death, specifically through caspase-3 and caspase-9 activation." (PMID 40217305, 2025). "This tumour‐promoting function of IL‐22 through STAT3 activation has also been demonstrated in HCC and NSCLC." (PMID 40899118, 2025). "Stabilised STAT3 increases the transcription of genes related to tumour cell growth and cell cycle progression." (PMID 39778006, 2025). "Previous studies have reported that STAT3, an oncogenic factor, can promote the proliferation and survival of tumor cells and increase their invasion and migration abilities." (PMID 40458725, 2025). "In BC, dysregulated activation of the JAK2/STAT3 signaling cascade promotes unregulated tumor proliferation, facilitates angiogenesis, enhances metastasis, and induces resistance to therapeutic agents." (PMID 41049266, 2025). "Functionally, the expression of SPINK1 is upregulated by inflammatory signals from the tumor microenvironment, particularly interleukin-6 (IL-6) Via the STAT3 pathway." (PMID 41465391, 2025). "Other types of CAR-T cells, such as 4/15NKG2D-CAR and IL-4/IL-21 ICR, also show anti-tumor activity; the former converts IL-4 inhibitory signals downstream into IL-15 activation signals, while the latter activates the STAT3 pathway." (PMID 39958351, 2025). "The secretion of the cytokine IL-6 can also activate the STAT3 signaling pathway, thereby influencing the entire process of tumor initiation and progression." (PMID 40487290, 2025). "STAT3-YAP/TAZ signaling in endothelial cells promoted tumor angiogenesis enabling tumor expansion, highlighting the complexity of YAP/TAZ signaling." (PMID 39936032, 2025).
tumor (continued). "This study reveals the novel role of tumor-derived exosomal lncRNA HEIH in regulating macrophages via the miR-98-5p/STAT3 axis, advancing understanding of TME-immune cell interactions in HCC therapy." (PMID 40352941, 2025). "Research has demonstrated that IL-6 expedites tumor cell proliferation by upregulating cyclins, downregulating the expression of the cyclin-dependent kinase inhibitor p21, and activating STAT3 protein." (PMID 40563367, 2025). "In immune suppression in cancer, aberrant STAT3 activity promotes tumor immune evasion by reprogramming metabolism in the tumor microenvironment." (PMID 40305224, 2025). "Phosphorylation of c-Jun N-terminal kinase (JNK) and signal transducer and activator of transcription 3 (STAT3) induced by dysbiotic gut microbiome can accelerate tumor growth." (PMID 39860065, 2025). "Ablation of STAT3 results in a marked reduction in both tumor volume and proliferation mediated by Shh signaling." (PMID 40399946, 2025). "Activation of the JAK2/STAT3 pathway has an important function in tumour formation and transformation, for example, in lung, breast and colorectal cancers." (PMID 40003568, 2025). "These TAM related effects coupled with the ability of CRC cells to produce IL-10 through STAT3 signaling promotes tumor growth, invasiveness, and aggressiveness." (PMID 40607405, 2025). "STAT3-mediated induction of autophagy ultimately endows tumor cells with resistance to chemotherapy." (PMID 40940319, 2025). "STAT3 also promotes tumor progression and immune evasion by driving tumor cell resistance to natural killer (NK) cell-mediated killing while also regulating NK cell functions, making it a critical target for improving NK cell-based cancer immunotherapies." (PMID 41155227, 2025). "Feedback loops involving proteins like KRAS or STAT3 can also accelerate tumor growth and render treatment more challenging." (PMID 40227591, 2025). "Following 72 h, enhancement of tumor formation was appraised in human MSCs (hAMSCs)-treated HT-29 cells by EGFR/c-Src/IRSp53/p-AKT/p-Stat3 signal network employing qRT-PCR, besides the Western blot technique, as well as the MTT and hanging drop assays." (PMID 41200137, 2025). "IL-6 and IL-1β can enhance CD274 expression in tumor cells by activating the JAK2/STAT3 signaling pathway, making it difficult to be recognized by T cells and facilitating tumor immune evasion." (PMID 39911394, 2025). "In HF, STAT3 activation promotes cardiomyocyte hypertrophy and fibrosis, whereas in cancer, it drives tumor growth, invasion, and resistance to apoptosis." (PMID 40924729, 2025). "For example, in tumor growth and dissemination, STAT3 activation controls FAK phosphorylation and MMP-2 activity." (PMID 40217305, 2025). "Collectively, these findings identify CAV1 as a central regulator of tumour dormancy-associated pathways and acquired TKI-resistance through modulation of E-cadherin, RAC1 and p21, alongside activation of the P70S6K and STAT3 pathways." (PMID 40715090, 2025). "Prominently, elevated levels of a variety of transcription factors linked with tumor progression, such as EGFR, FOXM1, STAT3, FGFR1, and GATA6, were identified in the high PANO subtype." (PMID 40918470, 2025). "Inhibition of STAT3 disrupts the transcription of genes involved in cell cycle progression and apoptosis, thereby inhibiting tumor cell proliferation." (PMID 40076318, 2025). "STAT3 activation also helps tumor cells evade host immune surveillance by upregulating the expression of immune checkpoint molecules, such as PD-L1." (PMID 40989587, 2025). "In NSCLC (A549 and H460) cells, UA inhibits the EGFR/JAK2/STAT3 pathway to reduce tumor angiogenesis, migration and invasion, promote apoptosis and induce cell cycle arrest at G0/G1 phase [1063]." (PMID 40490812, 2025). "By modulating the STAT3 pathway and tumor vasculature, SLC9A2 emerges as a potential prognostic biomarker and therapeutic target." (PMID 40474298, 2025).
tumor (continued). "Beyond direct effects on proliferation and survival, MT regulates multiple oncogenic and tumor-suppressor pathways, including Let-7, c-Myc, Ras, Wnt/β-catenin, and JAK/STAT3, thereby halting tumor growth and cell cycle progression." (PMID 40564074, 2025). "Blocking critical signaling pathways in HCC, such as STAT3/VEGF/HIF-1α.Prevent tumor growth and angiogenesis.Cell cycle arrest, especially in the S phase." (PMID 40430962, 2025). "The combination of sorafenib treatment with the transcriptional knockdown of STAT3 in a subcutaneous tumor model resulted in increased NK cell infiltration with enhanced antitumor activity." (PMID 40500404, 2025). "CUR affects the STAT3 pathway in mice by inhibiting its activation, leading to a reduction in tumor growth and angiogenesis." (PMID 40860906, 2025). "PRLR is known to activate multiple downstream signaling pathways, among which the JAK2/STAT3 pathway plays a crucial role in tumor cell proliferation, immune evasion, and therapeutic resistance." (PMID 40978029, 2025). "The role of the IRE1α/XBP1 signaling in the activation of IL-6-JAK-STAT signaling is also supported by the finding that myofiber-specific deletion of XBP1 strongly inhibited the phosphorylation of STAT3 in skeletal muscle of KPC tumor-bearing mice." (PMID 40655023, 2025). "STAT3, a member of the STAT transcription factor family, facilitates tumor progression by regulating genes associated with cell metabolism, survival, proliferation, metastasis, and immune evasion." (PMID 40242440, 2025). "From a mechanistic perspective, the inhibition of STAT3 phosphorylation is crucial for the synergistic anti‐tumor effects observed when combining IDET with paclitaxel." (PMID 40918170, 2025). "The ability of propolis to simultaneously target the HIF-1α, NF-κB, and STAT3 pathways underscores its unique potential to dismantle the signaling network that sustains the hypoxic and pro-inflammatory tumor microenvironment." (PMID 41302515, 2025). "The interaction between STAT3 and NF-κB also plays a crucial role in the dialogue between cancer cells and the tumor microenvironment, which facilitates the immune cell infiltration." (PMID 38478147, 2025). "For instance, CAFs secrete growth factors, cytokines, and exosomes that activate key signaling pathways such as phosphoinositide 3-kinase (PI3K)-Akt, NF-κB, and STAT3 in tumor cells." (PMID 40177538, 2025). "The further study found that the STAT1/STAT3 signaling pathway in tumor cells activated by IL-10 inhibited the PERK signaling pathway and alleviated the ER stress-mediated cell death in tumor cells caused by CAP treatment." (PMID 41145470, 2025). "Regarding therapeutic implications, the combined inhibition of HRH1 and STAT3 enhanced tumor-suppressive effects compared to HRH1 targeting alone in OSCC cells and a xenograft model." (PMID 40113769, 2025). "Preclinical studies has demonstrated that liraglutide enhances NK cell-mediated anti-tumor immune responses by inhibiting the IL-6/STAT3 signaling pathway in hepatocellular carcinoma cells and enhances NK cell functionality in obese patients." (PMID 40140925, 2025). "In metastatic tumor cells, STAT3 activation promotes chemoresistance and stimulates the release of growth factors that, in turn, activate STAT3 in astrocytes." (PMID 40733107, 2025). "These cytokines activate persistent NF-κB and STAT3 signaling, establishing a chronic pro-tumorigenic inflammatory state that fosters tumor cell survival, epithelial–mesenchymal transition, and immune evasion." (PMID 41487591, 2025). "STAT3 promotes tumor growth, inhibits apoptosis, accelerates angiogenesis and metastasis, facilitates immune evasion, and contributes to chemoresistance." (PMID 41031165, 2025).
tumor (continued). "To determine the role of the STAT3/UBE2S/NKp30 axis in vivo, we established a PC-9 subcutaneous tumor model using C-NKG mice deficient in T cells, B cells, and NK cells." (PMID 41254082, 2025). "IFN, in turn, contributes to tumor suppression by upregulating IL-6 and activating signal transducer and activator of transcription 3 (STAT3)." (PMID 41011273, 2025). "Our study identified STAT3 and C/EBPβ as key regulators to inhibit key chemokine expression, thus excluding T cell infiltration into tumor sites." (PMID 40749055, 2025). "In contrast, MYC, STAT3, CDH1, and CCND1 were significantly downregulated in tumor tissues compared to normal controls, suggesting a loss of tumor-suppressive or differentiation-related functions." (PMID 40766612, 2025). "MiR-21 acts as an oncomiR by engaging PI3K/AKT and STAT3 signaling, miR-145 exerts tumor-suppressive effects by constraining migration and epithelial–mesenchymal transition, while miR-106a influences cell growth, apoptosis, and autophagy." (PMID 41465474, 2025). "Higher cellular uptake, tumor penetration, and accumulation; significant tumor growth inhibition and extended survival in 4T1 murine model; high anti-inflammatory activity via STAT3 inhibition." (PMID 41011159, 2025). "IL-6 and IL-1β activate STAT3/NF-κB pathways in tumor cells, enhancing proliferation, invasion, and stemness." (PMID 41007766, 2025). "Sustained MAPK activation also triggers transcription factors like STAT3, enhancing tumor cell survival, invasiveness, and metastatic potential, exacerbating HCC malignancy and worsening patient prognosis." (PMID 40060195, 2025). "S1P promotes tumor cell drug resistance by activating the STAT3 pathway, while deoxycholic acid enhances metastatic potential by inducing DNA damage and oxidative stress." (PMID 41164182, 2025). "Xenografting CRISPR cells into immunodeficient mice indicated a crucial role for JAK1 and STAT3 in USP6-induced tumor development." (PMID 40348771, 2025). "Mechanistically, miR-876 directly targets SOCS4, activating the STAT3 signaling pathway, which subsequently upregulates PD-L1 expression, facilitating tumor immune evasion." (PMID 40140827, 2025). "In tumor therapy, TEVs play a significant role, such as enabling deep tumor penetration for drug delivery, exhibiting high specific homing capabilities, and activating the signal transducer and activator of transcription 3 pathway." (PMID 40496863, 2025). "For example, recent findings indicate that while STAT3 promotes tumor growth during the initial stages of SCLC, paradoxically, knocking out STAT3 can increase metastatic potential." (PMID 41194225, 2025). "To determine the degree of tyrosine phosphorylation of STAT1 and STAT3 in cultured tumor cells compared to normal controls, we performed Western blot experiments." (PMID 40287766, 2025). "EAC tumor progression significantly (p < 0.05) suppressed apoptotic signaling, reducing caspase-8 expression by 63.9% while markedly elevating proliferative STAT-3 levels (+ 668.4%) compared to normal controls." (PMID 41326498, 2025). "Several genes were similarly down-regulated in all T-LGLL, somewhat less markedly in STAT3-mutated cases, e.g. cluster 2 (149 genes, including key receptors like IL23R and KLRB1) and cluster 8 (46 genes, including tumor suppressors like BEND5 and TCEA3)." (PMID 40721648, 2025). "Both drug classes converge on critical signaling cascades, including the MAPK/ERK and STAT3 pathways, which are pivotal for tumor cell proliferation, survival, and migration." (PMID 40650282, 2025). "TPTEP1 suppresses the progression of HCC cells by affecting the IL-6/STAT3 signaling pathway, revealing its tumor-suppressive role in HCC chemotherapy." (PMID 40352941, 2025).